RBPJ (recombination signal binding protein for immunoglobulin kappa J region)
Diseases named in the same sentence as RBPJ in open-access papers (continued):
Sharing a sentence is not in itself a finding about the gene and the disease.
cancer (44 papers, 2008 to 2026). A tumor composed of atypical neoplastic, often pleomorphic cells that invade other tissues. "The relative expression level of the Notch signaling key TF RBPJ was upregulated in the PC datasets of The Cancer Genome Atlas (TCGA) database." (PMID 39725730, 2024). "RBPJ expression correlated with terminal exhaustion in CTLs from patients with cancer and from GEMMs, as well as with hyporesponsiveness to immunotherapies in individuals with cancer." (PMID 37968405, 2023). "One molecule, termed RBPJ INhibitor-1 (RIN1), potently disrupted the functional interaction of RBPJ with NOTCH and functioned as a probe of RBPJ function in cancer and skeletal myogenesis models." (PMID 31346210, 2019). "A previous ChIP-seq study reported these genes among candidate RBPJ targets in F9 embryonal carcinoma cells." (PMID 31031137, 2019). "DARDN identifies simulated regulatory sequences and known cancer TFs like RBPJ in T-ALL." (PMID 38397134, 2024). "Previous studies have reported the important role of RBPJ in cancers, indicating that rs9289981 may exert its function by influencing chromatin accessibility and regulating CMSS1 expression." (PMID 36330496, 2022). "The results suggested that RBPJ might function mainly via regulating DNA repair, metastasis, and hypoxia to inhibit cancer progression." (PMID 32039830, 2020). "Our results show that direct inhibition of RBPJ may offer a novel approach for inhibition of the Notch pathway not only in RMS but also in many cancers." (PMID 22792167, 2012). "RBPJ staining was indicated in the most of cancer and normal cells." (PMID 23181716, 2012). "Notch1 associates with these RBPJ binding sites after activation in liver bile duct carcinoma cells, and this interaction may promote Notch1-mediated regulation of POSTN transcription, as the Notch1/RBPJ complex is known to control cell fate decisions, proliferation, and differentiation in cancer." (PMID 41018265, 2025). "The Notch signaling pathway mediated by RBPJ is involved in various cellular processes, including cell fate determination, differentiation, proliferation, and apoptosis, and plays critical roles in embryonic development, tissue homeostasis, and disease processes, such as cancer and heart diseases." (PMID 39324142, 2024). "The correlation between PTEN and RBPJ, a vital protein of the Notch-1 pathway, was also confirmed using the GEPIA (GEPIA (Gene Expression Profiling Interactive Analysis) (cancer-pku." (PMID 38733531, 2024). "Since BEN domain could interact with RBPJ in Drosophila according to previous study 17, we speculated that RBPJ may be a potential BEND5 interaction partner in human cancer cells." (PMID 35844785, 2022). "In all cancer and non-cancerous cases predominantly moderate nuclear RBPJ and weak cytoplasmic staining was detected, however in some MBC and IDC cases strong nuclear staining was revealed." (PMID 23181716, 2012).
infection (24 papers, 2010 to 2025). The state of being infected such as from the introduction of a foreign agent such as serum, vaccine, antigenic substance or organism. "This suggests that the ability of EBNA3C to interact with RBPJ is important for the regulation of viral genes in the context of infection." (PMID 26751214, 2016). "Infection of primary CD19+ cells with this RBPJ BM EBNA3C-recombinant virus resulted in outgrowth and establishment of an LCL." (PMID 26751214, 2016). "This raises the question of precisely what role RBPJ plays in repression here, or more generally in the context of infections with other gamma-herpesviruses such as KSHV." (PMID 26751214, 2016). "Consistent with the results of the luciferase reporter assays and the ChIP studies, infection with the RBPJ BM EBNA3C virus was unable to repress ADAM28, ADAMDEC1 or COBLL1." (PMID 26751214, 2016). "However, we observed reconstitution of the PU.1 expression level in the nucleus of THP-1 cells which were treated with RBPjκ siRNA to inhibit Notch signaling before infection." (PMID 27381289, 2016). "This is the first time that EBNA3C-mediated transcriptional repression has been described in such detail and it provides novel insights into temporal sequence of events occurring early after infection and the dynamic role of RBPJ in EBV-mediated gene repression." (PMID 26751214, 2016). "In order to determine whether binding of EBNA3C to RBPJ is necessary for the repression of the endogenous COBLL1 and ADAM28-ADAMDEC1 locus in the context of infection, a new EBV recombinant encoding the RBPJ binding mutant of EBNA3C (RBPJ BM EBNA3C) was constructed." (PMID 26751214, 2016). "During de novo infection and lytic reactivation, as the relative expression levels of RTA and LANA changed, the expression of let-7a and RBPJ changed accordingly." (PMID 35069510, 2021). "Finally, in order to determine whether binding of EBNA3C to RBPJ was necessary for the repression of the endogenous COBLL1 and ADAM28-ADAMDEC1 locus, RNA samples taken every 5 days from the time of infection of primary B cells with the recombinant RBPJ BM EBNA3C virus were analysed." (PMID 26751214, 2016). "In the latent phase of infection, RBPJ does not bind to the promoters, but during viral reactivation the same promoters show a high degree of binding of RBPJ after RTA induction." (PMID 35164678, 2022). "Infection with Ad-CMV-Cre resulted in the deletion of Rbpj and the loss of the stimulatory effect of the NOTCH2 gain-of-function on the Notch target genes Hes1, Hey1, and Hey2 (not shown) since RBPJκ is required for their induction by Notch." (PMID 37865314, 2023). "Studies in transgenic mice unable to activate RBPJ because of dominant-negative MAML expression, showed that canonical Notch signaling is not involved in Th1 polarization, and similarly, in T-cells lacking RBPJ expression, the capacity to drive a Th1 cells in response to infection was maintained." (PMID 31191522, 2019). "As expected, the EBNA3C knockout (3C KO) and EBNA3C RBPJ BM (3C RBPJ BM) viruses failed to regulate the COBLL1 mRNA level, whereas EBNA3C-competent viruses (WT and 3C Rev) resulted in a rapid reduction of COBLL1 gene expression over a period of 30 days after infection." (PMID 30135119, 2018).
RBPJ also shares sentences with these, for which no sentence is quoted: Burkitt lymphoma (6 papers); colon cancer (6); Hepatic fibrosis (6); ischemia (5); atherosclerosis (4); leukemia (4); melanoma (4); diabetes (3); fibrosis (3); Stroke (3); asthma (2); brain ischemia (2); gouty arthritis (2); Hyperglycemia (2); Hyperkeratosis (2); hyperlipidemia (2); Obesity (2); oral cancer (2); ovarian carcinoma (2); renal fibrosis (2); T cell lymphoma (2); T-cell acute lymphoblastic leukemia (2); 22q11.2 deletion syndrome (1); Acute hepatitis (1); acute lymphoblastic leukemia (1); adenovirus infection (1); allergic asthma (1); aortic valve calcification (1); aortic valve diseases (1); aplasia cutis congenita (1).
A further 73 diseases each share a sentence with RBPJ in 1 paper.